TPM1 (tropomyosin 1)
Diseases named in the same sentence as TPM1 in open-access papers (continued):
Sharing a sentence is not in itself a finding about the gene and the disease.
glioma (9 papers, 2008 to 2023). A benign or malignant brain and spinal cord tumor that arises from glial cells (astrocytes, oligodendrocytes, ependymal cells). "TPM1 was found to be a mediator between 4’-acetamino-4-hydroxyl chalcone and its antitumor effects (including inhibition of angiogenesis) in glioma." (PMID 37686101, 2023). "For instance, the regulation of the tropomyosin 1 gene was suggested as a possible mechanism for decreasing the invasion of glioma cells when exposed to chalcone derivatives, but more studies are needed to establish this link." (PMID 34205043, 2021). "It has been reported that TPM1 overexpression combined with radiotherapy can significantly inhibit the growth of U251 xenografts, suggesting that TPM1 may be the mechanism of radiation resistance in glioma." (PMID 37686101, 2023). "The results showed that TPM1, TPM3, and TPM4 were significantly more highly expressed in glioma in comparison to normal tissues, while TPM2 mRNA expression showed no statistical differences." (PMID 35892971, 2022). "In this study, it was found that TPM1, TPM3, and TPM4 were significantly upregulated in gliomas, while a high expression level of TPM2, TPM3, and TPM4 was significantly correlated with poorer prognosis." (PMID 35892971, 2022). "The results showed that TPM2, TPM3, and TPM4 were more expressed in high-grade gliomas than in low-grade gliomas, while for TPM1, the trend was not as evident as in other groups." (PMID 35892971, 2022). "MiRNA-21 exerts its oncogenic function in gliomas through its post-transcriptional targets and downstream signal pathways: PDCD4, phosphatase and tensin homolog (PTEN), tumour protein 63 (TP63), tropomyosin 1 (TPM1), and tissue inhibitor of metalloproteases 3 (TIMP3)." (PMID 33610185, 2021).
heart failure (8 papers, 2008 to 2026). Inability of the heart to pump blood at an adequate rate to meet tissue metabolic requirements. "A 50-year-old female with a family history of sudden cardiac death, LVNC cardiomyopathy associated with TPM1 gene mutation, and recurrent hospitalizations due to heart failure was listed for heart transplantation." (PMID 40144250, 2024). "Focusing on tropomyosin, we observed that while the predominant cardiac gene TPM1 showed moderate up-regulation of its transcript isoforms, transcripts derived from TPM3-typically expressed at lower levels in the healthy heart-were markedly increased in heart failure." (PMID 41530494, 2026).
hepatocellular carcinoma (8 papers, 2022 to 2025). A malignant tumor that arises from hepatocytes. "Studies have shown that TPM1 expression levels are significantly elevated in hepatocellular carcinoma (HCC) and are associated with tumor invasiveness and patient prognosis." (PMID 40943308, 2025). "miR-21 is oncogenic miRNA that affects the expression of many cancer-related genes such as PTEN, RECK, TPM1, and PDCD in colorectal, breast, lung, prostate, gastric, hepatocellular carcinoma, and glioblastoma cancers." (PMID 41200944, 2025). "Our study detected the expression of TPM1–4 was all significantly upregulated in hepatocellular carcinoma (HCC), suggesting TPM1–4 may serve as an important role in HCC development." (PMID 34850589, 2022).
lung carcinoma (8 papers, 2020 to 2024). "In a study on lung cancer, the TPM1 gene was confirmed to inhibit the proliferation and invasion of lung cancer cells and enhance cell apoptosis through the regulatory effect of circ-RNAs." (PMID 37686101, 2023). "Cytoplasmic circ-0001320 is downregulated in lung cancer cells and inhibits the growth and invasion of lung cancer cells through the miR-558/TNFAIP1 and TPM1 pathways." (PMID 36338714, 2022).
colon cancer (7 papers, 2013 to 2025). "The TPM1 gene (encoding Tm2) is silenced in metastatic breast and colon cancer cell lines by promoter hyper-methylation." (PMID 26475688, 2015). "The immunohistochemistry analysis data derived from HPA showed that in colon cancer tissues, TPM1 expression was lower than that in normal tissues, and differences in the other six protein expression were statistically insignificant (Table." (PMID 34180352, 2021). "We found that the immunomodulator TGFBR1 showed positive correlation with TPM1 expression in colon cancer, and the immunomodulator TNFRSF25 showed negative correlation with TPM1." (PMID 34180352, 2021). "Studies have shown that TPM1 can increase the sensitivity of colon cancer cells to chemotherapy drugs and can exert an inhibitory effect on colon cancer cells, which is consistent with our findings." (PMID 34180352, 2021). "Additionally, seven genes were statistically related to prognosis in patients with colon cancer, and TPM1 provided a theoretical basis for co-targeting ICB and EMT-related gene expression." (PMID 34180352, 2021). "The expression of TPM1 in colon cancer cells was lower than that in normal cells." (PMID 34180352, 2021). "We identified seven EMT-related genes (TPM1, LAMC1, POSTN, CCN1, MGP, PCOLCE2, and DPYSL3) with prognostic significance in patients with colon cancer from TCGA and GSE17536 cohorts." (PMID 34180352, 2021). "We also report that several target genes of miR-21, such as, PDCD4, TPM1 and PTEN are down-regulated by exosomes from colon cancer cells, and, further, silencing of PDCD4 mimics the effects of miR-21 transfections." (PMID 32427870, 2020). "Thus, we examined the effect of exogenous TGFβ treatment on TAGLN expression, as well as on the expression of a number of TGFβ-responsive genes (ACTA2, and TPM1), in the RKO colon cancer cell model." (PMID 32393769, 2020).
renal cell carcinoma (6 papers, 2019 to 2023). "Moreover, TPM1 was conductive to restrain cell proliferation, angiogenesis and metastasis in renal cell carcinoma." (PMID 33653339, 2021). "Consistent with previous findings, miRNA-21 is overexpressed in renal cell carcinoma (RCC) tissues and regulates the growth, apoptosis, and cell cycle progression of RCC cells, as well as the expression of programmed cell death 4 (PDCD4) and TPM1." (PMID 37686101, 2023).
cervical cancer (5 papers, 2004 to 2022). A primary or metastatic malignant neoplasm involving the cervix. "TPM-1 was found to be downregulated in cervical cancer tissues in which microRN-21 is overexpressed." (PMID 35895593, 2022). "Previous studies revealed that PDCD4, PTEN and TPM1 are all transcripts targeted by mir-21 in various tissues and that PTEN is progressively underexpressed from normal tissue through to cervical cancer." (PMID 22194833, 2011). "In contrast, CK 17, a member of a family of intermediate filament proteins that are characteristic of epithelial cells as well as tropomyosin 1 (TM 1), were upregulated in normal vaginal tissue but not in both vaginal and cervical cancer." (PMID 15199389, 2004).
osteosarcoma (5 papers, 2020 to 2024). A usually aggressive malignant bone-forming mesenchymal neoplasm, predominantly affecting adolescents and young adults. "miR-107 promotes the survival, migration, and invasion of human osteosarcoma cells by regulating TPM1." (PMID 37686101, 2023). "Studies have shown TPM1 expression is dysregulated across several carcinomas, including gastric, bladder and osteosarcoma." (PMID 35477379, 2022). "The expression of miR-107 is up-regulated in osteosarcoma cells U2OS, and its overexpression promotes the survival, migration, and invasion of U2OS cells by down-regulating the TPM1-stimulated MEK/ERK and NF-κB signaling pathways." (PMID 37686101, 2023).
renal fibrosis (5 papers, 2015 to 2024). A final common manifestation of a wide variety of chronic kidney diseases characterized by glomerulosclerosis and tubulointerstitial fibrosis. "Additionally, in TPM1-deficient mice, miR-29c deficiency-induced upregulation of several fibrotic genes was abolished, and ameliorate renal fibrosis." (PMID 32346368, 2020). "Also, the observed negative association was further corroborated by the UUO mouse results, indicating that TPM1 expression was negatively associated with expression of miR-29c and renal fibrosis occurrence." (PMID 32346368, 2020). "In 2020, researchers found that miR‐29c reduced EMT and renal fibrosis through the TPM1‐mediated Wnt/β‐catenin pathway." (PMID 38898750, 2024). "Previous research has demonstrated that the microRNA miR29c alleviates renal fibrosis via TPM1-mediated suppression of the Wnt/β-catenin pathway." (PMID 35493725, 2022). "The results of this study show that TPM1 is a miR-29c target during renal fibrosis, and reciprocal expression of miR-29c and TPM1 has been found in both NRK-49F cells and mouse kidneys." (PMID 32346368, 2020). "It has been reported that miR-29b suppresses progression of renal fibrosis by down-regulating tropomyosin 1 and COL2A1." (PMID 25356754, 2015). "Next, we assessed the functional contributions of TPM1 on miR6-29c in renal fibrosis." (PMID 32346368, 2020). "Additionally, TPM1 exhibited the ability to regulate both TGF-β1-induced fibrosis and the Wnt/β-catenin pathway, indicating that targeting TPM1 by miR-29c may have a critical role in UUO-induced renal fibrosis." (PMID 32346368, 2020). "Therefore, it is reasonable to speculate that exosomes can carry miR‐29c to regulate the TPM1‐mediated Wnt/β‐catenin pathway, thereby regulating EMT and renal fibrosis, but this topic needs to be further studied." (PMID 38898750, 2024).
cardiac hypertrophy (4 papers, 2017 to 2023). "Genetic mutations in TPM1 are associated with cardiac hypertrophy, while genetic mutations in TPM2 were previously reported in patients with congenital myopathy." (PMID 36631981, 2023). "Mutations in TPM1 at chromosome 15 is associated with both the development of the metabolic syndrome and cardiac hypertrophy." (PMID 36138412, 2022). "Genetic variants of MYH6, TNNT2 and TPM1, have been found to be associated with hypoplastic left heart, cardiac hypertrophy and DCM, respectively." (PMID 32423033, 2020). "Down-regulation of calcium handling genes (e.g., Pln, Atp2a2) and adult forms of sarcomeric genes (e.g., Actc1 and Tpm1) is another gene expression signature of cardiac hypertrophy and failure." (PMID 28861005, 2017).
ovarian carcinoma (4 papers, 2017 to 2023). A malignant neoplasm originating from the surface ovarian epithelium. "It was reported that TPM1 expression was down-regulated in multiple cancers types, including renal, breast, esophageal, colorectal and ovarian cancer." (PMID 28182650, 2017).
pancreatic cancer (4 papers, 2017 to 2025). "However, TPM1 functions in pancreatic cancer and correlations with PDAC mediated liver metastasis need further study." (PMID 35477379, 2022). "Moreover, TPM1 has been shown to be notably reduced in pancreatic cancer patients and drug-resistant pancreatic cancer cell lines, and a low TPM1 level was correlated with worse survival." (PMID 28182650, 2017). "miR‐21 targets phosphatase and tensin homologue (PTEN), programed cell death 4 (PDCD4), tropomyosin 1 (TMP1), and tissue inhibitor of metalloproteinases 3 (TIMP3) genes in pancreatic cancer resulting in increased proliferation, invasion and chemoresistance." (PMID 39855897, 2025).
tongue squamous cell carcinoma (4 papers, 2017 to 2021). A squamous cell carcinoma that arises from the tongue. "Furthermore, Tropomyosin-1 (TPM1) has been demonstrated to function as a tumor suppressor gene in tongue squamous cell carcinomas." (PMID 33653339, 2021). "In tongue squamous cell carcinoma, upregulation of mir-21 could independently predict shorter survival of patients by modulating the expression of the tropomyosin 1 (TPM1) gene and inhibiting the apoptosis of tumor cells." (PMID 31766478, 2019). "Finally, research has shown that TPM1 expression in tongue squamous cell carcinoma is down-regulated." (PMID 28182650, 2017). "However, in this study, the researcher transfected TPM1-siRNA in tongue squamous cell carcinoma cell lines, which decreased the expression of TPM1, and the results indicated that there was no influence on cell survival or cell growth." (PMID 28182650, 2017).
Arrhythmia (3 papers, 2018 to 2022). Any cardiac rhythm other than the normal sinus rhythm. "Why do hiPSC-CMs with different HCM-causing mutations respond differently to endogenous adrenaline and why are VT types of arrhythmia exclusively presented in hiPSC-CMs with mutation in TPM1-Asp175Asn?" (PMID 29361520, 2018). "In addition, we observed ventricular tachycardia types of arrhythmias in hiPSC-CMs carrying the TPM1-Asp175Asn mutation." (PMID 29361520, 2018). "TBX5-targeted genes, MYH6, ACTC1 and TPM1, were involved in arrhythmia." (PMID 32423033, 2020). "However, in our hiPSC-CM study, we only observed VT types of arrhythmia in HCMT-CMs, thus our finding is in line with earlier clinical studies of patients with the TPM1-Asp175Asn mutation being at increased risk of arrhythmia." (PMID 29361520, 2018).
breast tumor (3 papers, 2020 to 2025). "It has been reported that high-grade breast tumor expresses significantly lower levels of TPM1 compared to normal tissues." (PMID 33193757, 2020).
cataract (3 papers, 2017 to 2021). Partial or complete opacity of the crystalline lens of one or both eyes that decreases visual acuity and eventually results in blindness. "Moreover, we have reported that the expression of Tpm1 and Tpm2 was induced/elevated in the HLECs of human cataracts with ASF, or so-called anterior subcapsular cataracts, and in human PCO tissues surgically removed from patients affected by non-traumatic dislocated intraocular lens (IOL)." (PMID 30304871, 2018). "In our previous study, Tpm1 and Tpm2 were upregulated in the multilayered, spindle-shaped LECs in a rat model of PCO, human cataracts with anterior subcapsular fibrosis, and human differentiated LECs in a dislocated lens capsule." (PMID 33918979, 2021). "We assessed the expression of isoforms from the Tpm1 and Tpm2 genes in a mouse and a rat model of PCO in vivo, and in LECs obtained from human subjects of various ages with cataracts." (PMID 30304871, 2018).
Obesity (3 papers, 2021 to 2024). Accumulation of substantial excess body fat. "A recent study reported that expression level of TPM1 was decreased in subjects with obesity after a high-fat diet, while it was increased after an antioxidant intervention due to a reduction in process mediated by oxidative stress." (PMID 38703299, 2024). "Therefore, it was suggested that obesity may damage the structure and function of the heart by down-regulating TPM1 expression." (PMID 38703299, 2024). "Therefore, it was speculated that obesity may damage heart structure and function by down-regulating TPM1 expression, while silybin can protect the heart by up-regulating TPM1 expression." (PMID 33785854, 2021).
renal carcinoma (3 papers, 2017 to 2022). A carcinoma arising from the epithelium of the renal parenchyma or the renal pelvis. "It was demonstrated that TPM1 suppresses tumor growth and proliferation as well as angiogenesis in renal carcinoma." (PMID 35216175, 2022). "Meanwhile, elevated expression levels of TPM1 can induce apoptosis and inhibit invasion in renal cancer cells." (PMID 28182650, 2017). "It was confirmed that down-regulation of TPM1 expression was an early event in renal cancer cells." (PMID 28182650, 2017).
Alzheimer disease (2 papers, 2022 to 2024). A progressive, neurodegenerative disease characterized by loss of function and death of nerve cells in several areas of the brain leading to loss of cognitive function such as memory and language. "TPM1 protein, involved in striated muscle contraction, decreased upon therapy; this indicates a potential benefit of the therapy as an increase in TPM1 levels has been identified as a systemic pro-aging factor in mouse retina and young mouse models of Alzheimer's disease." (PMID 39478832, 2024). "Interestingly, we observed TPM1 upregulation and the ectopic dendritic sprouting of RBCs and HCs in young mouse models of Alzheimer's disease, indicating a potential role of TPM1 in age‐related neurodegenerative diseases." (PMID 35148456, 2022).
arteriosclerosis (2 papers, 2018 to 2025). A vascular disorder characterized by thickening and hardening of the walls of the arteries. "The reduction of TPM-1 levels might also relate to the loss of AV flexibility, as occurs in arteriosclerosis, being indicative of the differentiation of the valvular interstitial cells to osteoblasts, which have no contractile ability." (PMID 29752279, 2018). "Moreover, a reduction in the expression of TPM-1 has been previously related to a decrease in the contraction of actin filaments in arteries with arteriosclerosis." (PMID 29752279, 2018). "Studies have reported that TPM1 regulates the dynamics and function of cytoskeletal actin filaments and inhibits VSMC proliferation and migration, suggesting that it exerts a protective effect in arteriosclerosis." (PMID 41004162, 2025).
atherosclerosis (2 papers, 2015 to 2021). A disease characterized by the build-up of fatty material and calcium deposition in the arterial wall resulting in partial or complete occlusion of the arterial lumen. "Additional in vivo studies are needed to gain a better understanding of the role of α-tropomyosin in atherosclerosis and angiogenesis, as well as to examine the potential of TPM1 as a candidate therapy target for proinflammatory vascular disorders." (PMID 34604206, 2021). "In the context of atherosclerosis, a potential downregulator of TPM1 could be the small noncoding microRNA miR21, as miR21 was the highest upregulated miRNA in a study of human atherosclerotic plaques." (PMID 26663990, 2015).
esophageal squamous cell carcinoma (2 papers, 2016 to 2020). Esophageal squamous cell carcinoma (ESCC) is a type of esophageal carcinoma (EC) that can affect any part of the esophagus, but is usually located in the upper or middle third. "In summary, miR-21 is overexpressed in esophageal squamous cell carcinoma and is negatively correlated with the expression of TPM1." (PMID 33193757, 2020).
hereditary cardiomyopathies (2 papers, 2019 to 2021). "Mutations in the tropomyosin 1 gene can cause hereditary cardiomyopathies, left ventricular hypertrophy, or diastolic function disorders in the absence of hypertension and aortic stenosis." (PMID 34948066, 2021). "Mutations in the tropomyosin 1 gene can cause hereditary cardiomyopathies, hypertrophy of the left ventricle, or disturbances of the diastolic function in the absence of hypertension and aorta stenosis." (PMID 31703357, 2019).
intrahepatic cholangiocarcinoma (2 papers, 2022 to 2023). A carcinoma that arises from the intrahepatic bile duct epithelium in any site of the intrahepatic biliary tree. "However, another study showed that TPM1 expression was down-regulated in intrahepatic cholangiocarcinoma (ICC) compared with adjacent normal tissues." (PMID 37686101, 2023).
keloid (2 papers, 2013 to 2023). An irregularly shaped, elevated mark on the skin caused by deposits of excessive amounts of collagen during wound healing. "However, our results are innovative in revealing early wound healing-related genes (EPB41, TPM1, NF2, PARD3) in keloid patients from the perspective of alternative splicing regulated by RBP." (PMID 36777722, 2023). "We suggest that upregulation of the alternative splicing gene TPM1 in KPI may have a great effect on the local inflammatory response and excessive migration and proliferation of fibroblasts in keloid, and may be a potential therapeutic target for keloid." (PMID 36777722, 2023).